SIPA1 (signal-induced proliferation-associated 1)
Diseases named in the same sentence as SIPA1 in open-access papers (continued):
Sharing a sentence is not in itself a finding about the gene and the disease.
leukemia (2 papers, 2018 to 2019). A malignant (clonal) hematologic disorder, involving hematopoietic stem cells and characterized by the presence of primitive or atypical myeloid or lymphoid cells in the bone marrow and the blood. "While the physical interaction of lncRNA MALAT1 with the SIPA1 leukemia oncogene has been experimentally validated and recapitulated in our network, MALAT1 is linked to other crucial oncogenes in the two linked modules, and co-expressed with NEAT1, another well-known lncRNA in the context of cancer." (PMID 31142264, 2019). "The resistance of Sipa1−/− mice was apparently selective for Bcr-Abl+ CML in that Sipa1−/− mice were comparably susceptible to other leukemia cells without Bcr-Abl expression relative to Wt mice." (PMID 29500416, 2018). "Essentially similar results were obtained when Sipa1−/− mice were subcutaneously challenged with BA-1 cells, whereas EL4 leukemia cells formed progressive tumors comparably in both Sipa1−/− and Wt mice." (PMID 29500416, 2018).
Breast Invasive Carcinoma (1 paper, 2022). "By analysing the transcriptome data of 1100 Breast Invasive Carcinoma (BRCA) samples in The Cancer Genome Atlas Program (TCGA) database, we found that the mRNA expression level of SIPA1 positively correlated with macrophage abundance and pan-macrophage marker CD68." (PMID 35453742, 2022).
esophageal squamous cell carcinoma (1 paper, 2024). Esophageal squamous cell carcinoma (ESCC) is a type of esophageal carcinoma (EC) that can affect any part of the esophagus, but is usually located in the upper or middle third. "In esophageal squamous cell carcinoma (ESCC), ZNF750 suppresses ITGB1 transcription while SIPA1 inhibits the ITGB1 expression." (PMID 38279122, 2024).
glioma (1 paper, 2022). A benign or malignant brain and spinal cord tumor that arises from glial cells (astrocytes, oligodendrocytes, ependymal cells). "We aimed to analyze the regulatory effects of SIPA1 (signal-induced proliferation-associated protein 1) on glioma progression and the dominant signaling pathway." (PMID 35431649, 2022). "This study aims to explore the regulatory effects of SIPA1 on glioma and the dominant signaling pathway." (PMID 35431649, 2022). "Compared with normal brain tissues, mRNA and protein levels of SIPA1 were remarkably upregulated in glioma." (PMID 35431649, 2022). "SIPA1 is upregulated in glioma, which boosts malignant progression of glioma by activating the phosphorylation of the FAK signaling pathway." (PMID 35431649, 2022). "In the present study, SIPA1 was highly expressed in glioma cases, which boosted migratory and proliferative capacities of glioma cells and inhibited cell apoptosis." (PMID 35431649, 2022). "Knock-down of SIPA1 reduced migratory and proliferative rates of glioma cells, increased apoptotic cell rate, and declined cell ratio in the S phase." (PMID 35431649, 2022). "SIPA1 is upregulated in glioma that boosts migratory and proliferative potentials of glioma cells by activating the phosphorylation of the FAK signaling pathway." (PMID 35431649, 2022). "A172 cells were used for the following experiments since they expressed a relatively high abundance of SIPA1 in the three tested glioma cell lines." (PMID 35431649, 2022). "The treatment of PF-56271 abolished the boosted proliferative ability of glioma by overexpression of SIPA1." (PMID 35431649, 2022). "Secondly, in vivo experiments are lneeded to verify the tumorigenic role of SIPA1 in glioma." (PMID 35431649, 2022). "In addition, SIPA1 upregulated phosphorylated FAKs in A172 cells and thus boosted malignant phenotypes of glioma." (PMID 35431649, 2022). "Meanwhile, SIPA1 was more highly expressed in glioma cell lines than astrocytes." (PMID 35431649, 2022). "Overexpression of SIPA1 markedly enhanced migratory and proliferative potentials of glioma cells." (PMID 35431649, 2022). "Differential level of SIPA1 in glioma and normal tissues and cells was determined." (PMID 35431649, 2022). "Flow cytometry data showed that the knockdown of SIPA1 in A172 cells arrested cell cycle progression in the G1 phase, which was further supported by the downregulation of cell cycle proteins Cyclin A2, Cyclin D1 and Cyclin E1 in glioma cells with SIPA1 knockdown." (PMID 35431649, 2022).
gout (1 paper, 2024). A condition characterized by painful swelling of the joints, which is caused by deposition of urate crystals. "We identified 22 methylation sites associated with gout, in which multiple methylation sites on SLC2A9 and SIPA1 were regulated, thereby influencing gout disease." (PMID 38831441, 2024).
liver cancer (1 paper, 2020). An epithelial or non-epithelial malignant neoplasm that arises from the liver. "The results indicated that FASN was closely associated with liver cancer migration and invasion, and interacted with FSCN1, SIPA1, SPTBN1 and CD59." (PMID 32699531, 2020). "In the current study, FSCN1 and SIPA1 were significantly downregulated following FASN knockdown in liver cancer cells." (PMID 32699531, 2020). "Furthermore, co-precipitation and co-localization of FASN with FSCN1 and SIPA1 in liver cancer indicated that FASN may mediate tumor metastasis via the PI3K/NF-κB/MMPs signaling pathway through interactions with FSCN1 or SIPA1." (PMID 32699531, 2020). "Knockdown of FASN in liver cancer reduced the expression of FSCN1, SIPA1, SPTBN1 and CD59." (PMID 32699531, 2020).
lung adenocarcinoma (1 paper, 2021). A carcinoma that arises from the lung and is characterized by the presence of malignant glandular epithelial cells. "With regard to the main histological types of lung cancer, the results from this cohort showed that in patients with lung adenocarcinoma, those with a low level of SIPA1 tended to have longer survival." (PMID 33917539, 2021). "Survival data of patients with lung adenocarcinoma cancers from the Kaplan Meier plotter website showed high SIPA1 level was accompanied by a poor outcome from cancer in terms of both OS (p = 0.0021) and PFS (p = 0.0065)." (PMID 33917539, 2021).
lung carcinoma (1 paper, 2021). "The role of Signal Induced Proliferation Associated 1 (SIPA1) in lung cancer remains largely unknown." (PMID 33917539, 2021). "During this study a series of functional assays were performed in order to find out more about the role of SIPA1 in the function of lung cancer cells." (PMID 33917539, 2021). "This study showed that knockdown of SIPA1 reduced the response of lung cancer cells to HGF in terms of invasion and barrier function." (PMID 33917539, 2021). "HGF decreased the barrier function of lung cancer cells, which was counteracted by SIPA1 knockdown with similarity to the small molecule MET targeted inhibitor, Crizotinib." (PMID 33917539, 2021). "This study aimed to evaluate the importance of SIPA1 in the development and progression of lung cancer, to demonstrate the cellular functions of SIPA1 and the molecular mechanisms involved." (PMID 33917539, 2021). "The findings of this study suggest that the expression of SIPA1 in lung cancer cells is closely related to the expression of TJ molecules and the cell’s barrier function." (PMID 33917539, 2021). "Transcript expression of SIPA1 in lung cancer tissue was determined in the cohort, collected at the Peking University Cancer Hospital, using qPCR." (PMID 33917539, 2021). "The transcript level of SIPA1 in stage T-3 lung cancer was statistically significantly higher than that in stage T-1 and T-2 tumours." (PMID 33917539, 2021). "The other mechanisms by which SIPA1 regulates the tight junctions of lung cancer cells require further exploration." (PMID 33917539, 2021). "SIPA1 gene expression was studied in the Peking lung cancer cohort and the TCGA database." (PMID 33917539, 2021). "From the prognostic analysis of lung cancer database, the median survival time of patients with high SIPA1 expression was significantly shorter than that of patients with low SIPA1 expression, and the difference is particularly significant in patients with adenocarcinoma." (PMID 33917539, 2021). "In SK-MES1 lung cancer cells, qPCR showed the transcript level of MET was actually higher in SIPA1-KD cells compared to pEF-CT cells." (PMID 33917539, 2021). "The in vitro trans-well invasion assay showed the invasion potential was markedly reduced after knockdown of SIPA1 in A549 and SKMES1 lung cancer cell lines." (PMID 33917539, 2021). "This project, therefore, aimed to evaluate the interaction between SIPA1 and HGF/MET, as well as their influence on lung cancer in terms of molecular activation, cellular behaviour and clinical relevance." (PMID 33917539, 2021). "However, there are limited studies investigating the function of SIPA1 in lung cancer and the mechanism of SIPA1 in cancer development and metastasis remains largely unknown, particularly the role of SIPA1 in regulating the TJs and reacting to HGF signaling in lung cancer cells." (PMID 33917539, 2021). "In conclusion, SIPA1 plays an essential role in NSCLC tumorigenesis and metastasis, by enhancing invasion and proliferation and suppressing the barrier function of lung cancer cells." (PMID 33917539, 2021). "RT-PCR and qPCR showed that the transcript level of MET was not influenced by knockdown of SIPA1 in A549 lung cancer cells." (PMID 33917539, 2021). "Comprehensive analysis of the TNM stage of the lung cancers, showed that TNM2 tumours had higher SIPA1 transcript levels than stage TNM1 tumours, and SIPA1 transcript levels in TNM2-3-4 stage was comprehensively higher than in the TNM1 tumours, but the difference was not statistically significant." (PMID 33917539, 2021). "In vitro cell function assays were performed after knock down of SIPA1 in lung cancer cells with/without treatment." (PMID 33917539, 2021). "Therefore, we can conclude that in lung cancer cells, Grb2, SCOS and PKCμ are the potential target molecules for SIPA1, thus promoting the recycling of MET, in order to maintain the MET receptor at a high level, thereby enabling the transmission of the HGF signal within the cells." (PMID 33917539, 2021).
lymph node metastasis (1 paper, 2009). "A preliminary human pilot epidemiology study indicated that germline single nucleotide polymorphisms of SIPA1 are significantly correlated to major clinical factors, such as estrogen receptor status and increased lymph node metastasis." (PMID 19765277, 2009). "A previous human epidemiology pilot study showed that SNPs (rs931127, rs3741378 and rs746429) from the SIPA1 gene are associated with important clinical markers such as oestrogen receptor status and lymph node metastasis." (PMID 19765277, 2009). "Germline SIPA1 SNPs showed association with positive lymph node metastasis and hormonal receptor status in a Caucasian cohort." (PMID 19765277, 2009).
metastatic cancer (1 paper, 2020). A carcinoma which has spread from the original site of growth to another anatomic site. "The mechanism underlying Sipa1 promoter hypomethylation in metastatic cancer cells has not been elucidated yet." (PMID 32193333, 2020).
myeloproliferative disorder (1 paper, 2006). A clonal hematopoietic stem cell disorder, characterized by proliferation in the bone marrow of one or more of the myeloid (i.e., granulocytic, erythroid, megakaryocytic, and mast cell) lineages. "For example, SIPA1-deficient mice develop a spectrum of symptoms resembling those seen in human myelodysplastic and myeloproliferative disorders." (PMID 16563182, 2006).
non-small cell lung carcinoma (1 paper, 2021). A group of at least three distinct histological types of lung cancer, including non-small cell squamous cell carcinoma, adenocarcinoma, and large cell carcinoma. "SIPA1 may also be a potential therapeutic target for non-small cell lung cancer (NSCLC) patients with aberrant MET expression and drug resistance." (PMID 33917539, 2021).
squamous cell carcinoma (1 paper, 2021). A carcinoma arising from squamous epithelial cells. "However in patients from the Peking cohort with squamous cell carcinoma, those with a low level of SIPA1 tended toward a worse prognosis without statistical significance; and data from the Kaplan Meier plotter website also lacked statistical significance." (PMID 33917539, 2021).
tumor (19 papers, 2006 to 2025). "SIPA1 (signal-induced proliferation-associated protein 1) is a protein relevant to tumor invasiveness and metastasis." (PMID 35431649, 2022). "We found that the decreased tumor volume caused by SIPA1 knockdown was offset by overexpression of LINC01615." (PMID 36230738, 2022). "Previous studies have shown that SIPA1 is closely associated with the adhesion, invasion and metastasis of tumor cells." (PMID 32193333, 2020). "Here the authors show that deficiency of the Rap1 GTPase-activating protein Sipa1 in the tumor microenvironment releases an immune response that eradicates CML-initiating cells via interplay between stromal and T cells." (PMID 29500416, 2018). "Altogether, these results suggest that Sipa1−/− MSCs exhibit enhanced migration directed to Bcr-Abl+ cells and secretion of Cxcl9, which causes efficient recruitment of Sipa1−/− memory T cells to the vicinity of the tumor cells." (PMID 29500416, 2018). "Polymorphisms in several other tumor cell autonomous metastasis susceptibility genes identified in our laboratory including Sipa1, Rrp1b, and Brd4 are prognostic only in ER+ patients, and stable expression of Brd4 can also differentially regulate the Tpx2 network." (PMID 22693453, 2012). "Specifically, tumor development in a background of germline-encoded SIPA1 dysfunction may enhance the ability of tumor cells to escape the primary lesion through alteration in cell morphology/polarity and/or by weakening the strength of intercellular contacts." (PMID 16563182, 2006). "In this study, we found a significant correlation between SIPA1-regulated lncRNA and tumor metastasis." (PMID 36230738, 2022). "Studies have reported that the SIPA1 protein can accelerate the development of tumors by regulating the adhesion and infiltration of various tumor cells." (PMID 36230738, 2022). "More and more evidence shows that SIPA1 not only regulates tumor occurrence and development through intermolecular interaction but also regulates gene transcription in the nucleus." (PMID 36230738, 2022). "Signal-induced proliferation-associated 1 (SIPA1), a member of Rap1GAP family, promotes aerobic glycolysis by regulating the SIPA1/HIF-2α/PDK1 axis, leading to tumor invasion and metastasis in vivo." (PMID 36532768, 2022). "Previous studies have shown that the interaction between SIPA1 and several molecules is known to regulate cell proliferation and migration and can provide potential models for studying the process of tumor metastasis, such as BRD4." (PMID 36230738, 2022). "The protein level of SIPA1 in tumour tissue samples was higher than that in normal lung tissue and adjacent normal lung tissue, but the difference was not statistically significant (data not shown)." (PMID 33917539, 2021). "Four proteins (FSCN1, SIPA1, SPTBN1 or CD59) closely associated with tumor metastasis interacted with FASN and exhibited decreased expression in response to FASN silencing." (PMID 32699531, 2020). "Although control Sipa1−/− mice showed transient tumor growth, those that rejected the tumors developed only negligible tumors, suggesting an effective memory response." (PMID 29500416, 2018). "Sipa1−/− mesenchymal stroma cells (MSCs) show enhanced activation and directed migration to Bcr-Abl+ cells in tumor tissue and preferentially produce Cxcl9, which in turn recruits Sipa1−/− memory T cells that have markedly augmented chemotactic activity." (PMID 29500416, 2018). "Activation of Sipa1−/− MSCs was only transient and contracted as the tumor cell burdens began to decrease at a later stage." (PMID 29500416, 2018). "We have previously shown that a relationship between BRD4-LF, RRP1B and SIPA1 is critical for tumor progression and extracellular matrix regulation." (PMID 24260471, 2013).
tumor (continued). "SIPA1 could be a key factor for tumour metastasis and recurrence in breast, colorectal, prostate, and lung cancer." (PMID 35453742, 2022). "In almost all tumor types studied, the expression level of SIPA1 is correlated with lymph node metastasis, indicating that SIPA1 may be a molecule related to tumor development and patient prognosis." (PMID 36230738, 2022). "Whether SIPA1 can be used as a reliable prognostic marker molecule or even a tumor therapeutic target still needs more laboratory and clinical studies." (PMID 36230738, 2022). "In hematological malignancies, SIPA1 acts as a tumor-suppressor gene." (PMID 35431649, 2022). "SIPA1 has been shown to work as a driving factor in a variety of tumours." (PMID 33917539, 2021). "The Sipa1 CpG regions of the tumor cell lines were methylated to different degrees." (PMID 32193333, 2020). "Furthermore, we compared the methylation status of the CpG island within the Sipa1 promoter-proximal elements among ten different tumor cell lines by MSP." (PMID 32193333, 2020). "Notably, Sipa1−/− tumor tissue also contained a high level of Ccl5, another potential T-cell chemokine, although the Ccl5 expression was negligible in Sipa1−/− MSCs." (PMID 29500416, 2018). "However, further experiments will be required to confirm the role of SIPA1 germline variation in modulating tumor progression efficiency, the most obvious of which is to replicate the associations seen here in other populations." (PMID 16563182, 2006). "Although the specific mechanism by which SIPA1 modulates metastatic efficiency is currently unclear, it is worthwhile to speculate on how observations of SIPA1 functionality in mice and humans may relate to the process of tumor progression and characterization." (PMID 16563182, 2006). "In terms of tumorigenesis, the Peking clinical cohort data showed that the transcription level of SIPA1 was significantly higher in the advanced T stage and TNM stage tumours." (PMID 33917539, 2021). "In terms of the substage, SIPA1 levels in TNM 1A and 1B tumours were lower than those in TNM 2B which had increased metastasis; and the difference was statistically significant." (PMID 33917539, 2021). "Knocking down either SIPA1 or HIF-2α significantly inhibited the invasion of MDA-MB-231 cells in vitro and the tumor cell translocation was further inhibited by the treatment with 20 mM oxamate." (PMID 35096814, 2021). "To assess the activation status of MSCs in tumor tissues, we sorted the GFP− CD45− CD31− Ter119− cell populations mostly representing mesenchymal cells from Bcr-Abl+ tumors of Wt and Sipa1−/− mice for comparative DNA microarray." (PMID 29500416, 2018). "Alternatively, SIPA1 polymorphism might facilitate nodal metastasis independent of tumor size." (PMID 16563182, 2006). "Also, SIPA1 knockdown decreased the expressions of EPAS1, glycolysis-related products and PDK1 in tumor tissues at mRNA and protein levels." (PMID 35096814, 2021). "Rrp1b may therefore mediate tumor cell adhesion properties by altering intercellular and cell–ECM contacts in a Sipa1-dependent and Rap1-dependent manner." (PMID 18081427, 2007). "We previously demonstrated the significant influence of germline variation on tumor progression, which allowed us to identify the first known heritable mouse gene that modulates metastasis, the Rap-GTPase activating protein (GAP) Sipa1." (PMID 18081427, 2007).